VHL (von Hippel-Lindau tumor suppressor)
Diseases named in the same sentence as VHL in open-access papers (continued):
Sharing a sentence is not in itself a finding about the gene and the disease.
cancer (continued). "Although WSB1 and E2-EPF expression is associated with cancer progression, they were both identified to interact with VHL and promote its ubiquitination and proteasomal degradation also in normoxic conditions in the human embryonic kidney or renal carcinoma cells." (PMID 34209205, 2021). "In line, detailed survival analysis in our cohort indicated significantly worse cancer-specific survival probability for patients with metastases harbouring multiple somatic drivers and VHL wildtype alleles compared to PBRM1, SETD2, and VHL monodrivers (p (logrank) = 0.03)." (PMID 34944839, 2021). "According to our bioinformatics analysis, the variant allele of rs1642742, which is residing in the 3′UTR of the VHL gene, associated with a variety of benign and malignant tumors, may attenuate the expression of VHL via strengthen its binding with miRNAs." (PMID 34477178, 2021). "In this way, TBK1, distinct from its innate immune signaling role, might serve as a novel target with therapeutic potential for cancers with VHL loss." (PMID 33142830, 2020). "Our findings indicated that the up‐regulation of NDRG1 by HIF‐1/2α may counteract the cancer‐promoting effect of HIF‐1/2α in VHL‐deficient ccRCC." (PMID 32537867, 2020). "VHL-deficient cancer cells are dependent on Glut1 and aerobic glycolysis for ATP production." (PMID 33053779, 2020). "Another study showed an association between NEK8 and VHL in cancer cells." (PMID 32294979, 2020). "Notably, cancer cells with VHL mutations exhibited greater dependence on GPX4 than VHL wildtype cells in a pan-cancer DepMap analysis." (PMID 30962421, 2019). "Exposure to TCE has been associated with a variety of cancers and disorders, including renal cancers and renal injury and has been associated with a specific mutation in the Von Hippel-Lindau syndrome (VHL) gene." (PMID 30898898, 2019). "VHL-deficient cancer cells depend on Glut1 and aerobic glycolysis for ATP production." (PMID 31597342, 2019). "To extend our findings of impaired homologous recombination in VHL-deficient cancer cell lines to human tumors, we interrogated The Cancer Genome Atlas (TCGA) Kidney Renal Clear Cell Carcinoma database to analyze DNA repair gene expression in VHL-deficient and VHLWT human renal tumor samples." (PMID 29435132, 2018). "Germline VHL mutations induce different phenotypes of cancer." (PMID 30477447, 2018). "Interestingly, chromosome 3p loss and, when present, VHL point mutations are always on the trunk of the phylogenetic tree, suggesting that they are key early events in cancer development." (PMID 29656891, 2018). "VHL is a rare (incidence of 1:36,000 in the general population) autosomal-dominant inherited syndrome associated with the development of a variety of benign and malignant tumours." (PMID 29166454, 2017). "We searched PUBMED, MEDLINE and EMBASE for articles including following terms in their titles, abstracts, or keywords: ‘kidney or renal’, ‘carcinoma or cancer or neoplasm or malignancy’, ‘von Hippel-Lindau or VHL’, ‘alteration or mutation or methylation’, and ‘prognostic or predictive’." (PMID 28103578, 2017). "Germline mutations of the VHL gene predispose affected individuals to the development of benign and malignant tumors in several systems including the central nervous system (CNS), and visceral organs such as the kidneys, pancreas, adrenals, and reproductive organs." (PMID 28785532, 2017). "This balance may be highly context specific, as is suggested by the organ specificity of VHL-associated cancer." (PMID 28315322, 2017). "However, the rates of apoptosis induced by 2DG-ABT were lower in von Hippel-Lindau (VHL)-deficient cancer cells." (PMID 27460078, 2016). "Importantly, there are lots of reports suggested that Sunitinib exhibited excellent efficiency in different cancers with VHL disease, which results from a mutation in VHL gene." (PMID 27974690, 2016).
cancer (continued). "Thus far, we showed that the AF2240 virulent strain of NDV caused degradation of HIF-1α and VHL in infected cancer cells." (PMID 27902314, 2016). "Furthermore, VHL-deficient cancer cells activate many of the same hypoxia-induced factors, even in the presence of normal levels of oxygen." (PMID 27460078, 2016). "Whether GA inhibits any of these cancer-associated proteins to stabilize VHL expression remains to be determined." (PMID 28326255, 2015). "Cancer may develop after shutting down of the function of VHL gene, when A allele is changed to G allele, followed by methylation of the CpG island." (PMID 25217002, 2014). "This seemed to disagree with a report that a class of compound, exemplified by STF-31, could directly bind and inhibit GLUT1 function and selectively kill VHL-deficient RCC cancer cells." (PMID 24260413, 2013). "Interestingly, ELR510444 possessed greater efficacy against VHL-deficient cancer cells compared to VHL+/+ cell lines." (PMID 22295124, 2012). "Whether VHL loss in cancer cells affects immune cells in the TME remains unclear." (PMID 38618956, 2024). "Notably, N-Scores in this work can precisely predict the mutation levels of VHL, which may help assessing the cancer progression of ccRCC." (PMID 36171882, 2022). "Thus, this essential role of ZMYND8 in regulating the gene activator function of EZH2 might represent a viable target for the effective treatment of cancers under hypoxia or with VHL deficiency, such as ccRCC." (PMID 33593912, 2021). "According to the genetic theory of cancer, VHL may be the driver, the cause, and the maker of RCC." (PMID 34439162, 2021). "Thus, we further investigated whether the VHL-R167Q mutation, through its capacity to induce pseudo-hypoxia, may result in the induction of genes associated with cancer cell stemness." (PMID 34359798, 2021). "Lastly, in the publicly available CRISPR-Cas9 screens that we have analyzed, the current small numbers of cell lines with mutations in other cancer drivers, such as VHL, limits our ability to reliably determine whether these cancer genes could also be selected during CRISPR-Cas9 genome editing." (PMID 34764240, 2021). "In order to explore whether the overexpression of these genes was related to hypoxia-inducible factor (HIF), we detected HIFα and its downstream proteins vascular endothelial growth factor A (VEGFA) and glucose transporter 1 (Glut1) in VHL mutated carcinoma and para-carcinoma tissues." (PMID 33828526, 2021). "Thus, STAG1-directed small molecule degraders that engage a suitable human E3 ligase such as VHL or CRBN may provide a promising therapeutic modality for the treatment of STAG2-mutated cancers." (PMID 32467316, 2020). "Therefore, we speculate that the balance of these two opposing roles of VHL might be associated with cancer initiation." (PMID 32284789, 2020). "Thus, this chemical would be useful for anti-cancer drug for VHL-deficient RCC and Breast." (PMID 27147573, 2016). "Therefore, we aimed this study at evaluation of the association between VHL status (VHL expression, mutations and promoter methylation), and a variety of demographic and cancer characteristics in a group of 264 Serbian patients admitted to our reference center for PTC from 1992 to 2008." (PMID 25490036, 2014). "Hence, mutation of VHL may result in upregulation of p160 and protection against apoptosis, which would provide a selective advantage to cancer cells." (PMID 21386990, 2011). "We further extended this framework to five additional cancer-related genes (VHL, ATM, BRCA1, RAD51C, and BAP1), establishing a generalizable framework for gene-specific VEP with potential applications in precision medicine." (PMID 41955512, 2026). "Its close paralog, WSB1, is induced by hypoxia and can form a CRL5WSB1 complex that promotes cancer metastasis by inducing VHL degradation." (PMID 40699886, 2025). "VHL is characterized by the development of numerous benign and malignant tumors, along with cysts in other organs." (PMID 39897240, 2025).
cancer (continued). "VHL loss and uncontrolled HIF activity contribute to the metabolic rewiring of cancer cells by enhancing the glycolytic flux and inhibiting oxidative phosphorylation (OXPHOS)." (PMID 41301058, 2025). "Loss of VHL function leads to the accumulation of HIF and the activation of hypoxia-responsive genes, contributing to tumor angiogenesis and cancer progression." (PMID 39851497, 2025). "This technique involves coupling a folate group to Von Hippel–Lindau (VHL) ligands, which enables cancer cell‐specific delivery and targeted degradation of POIs within cancer cells." (PMID 39898116, 2025). "Hypoxia-inducible factors 1 and 2 alphas, regulated by the VHL gene, can increase the levels of vascular endothelial growth factor, thereby activating cancer progression." (PMID 40005423, 2025). "Here, we describe a heterobifunctional degrader that promotes efficient K48-linked ubiquitination and complete depletion of endogenous IRE1 through VHL in cancer cells." (PMID 41381506, 2025). "By triggering the formation of a ternary complex involving STAT3, D-PROTAC, and the E3 ligases VHL, STAT3 undergoes efficient degradation in cancer cells via a mechanism reliant on both the E3 ligases VHL and the proteasome." (PMID 40118821, 2025). "In this study, we demonstrate that the VHL gene can be added to this group, as it is involved in both cancer development and stem cell regulation." (PMID 41301058, 2025). "Further research is essential for the development of effective therapies for cancers driven by VHL dysfunction." (PMID 40576306, 2025). "As a pivotal regulator of cancer and inflammation, the role of Von Hippel-Lindau (VHL) in hepatic I/R injury remains undetermined." (PMID 39585306, 2024). "Themolecules are based on connecting a known MYC binder to a VHL ligandor pomalidomide to induce MYC degradation in various cancer cellsknown to express MYC." (PMID 39698270, 2024). "VHL is usually mutant in a variety of cancers, such as clear cell carcinoma of renal cancer (ccRCC)." (PMID 38914543, 2024). "Typically, VHL is distinguished by the development of numerous benign and malignant tumors, alongside cysts affecting multiple organs." (PMID 39201746, 2024). "HIF1α and HIF2α are broadly expressed in many human cancers and are the most important downstream biomolecules of VHL." (PMID 38263248, 2024). "Alterations of VHL lead to impaired degradation of hypoxia-inducible factor 1α (HIF1α) and HIF2α promoting neoangiogenesis, which is pivotal for cancer growth." (PMID 39858553, 2024). "DT2216exploits VHL, a minimally expressed ligase in platelets, to degradeBCL-xL in cancer cells, thereby avoiding the platelet toxicity observedwith traditional BCL-xL inhibitors." (PMID 38990186, 2024). "Cancer somatic mutations significantly impacted the stability of complexes formed by key RCC drivers, including VHL, TCEB1, and NRF2, highlighting the critical role of these mutations in RCC development." (PMID 37964489, 2024). "In this study, UBE3B is unveiled as a novel substrate of VHL, providing additional therapeutic options for cancer treatment." (PMID 38914543, 2024). "In this study, we reveal the cyclin-dependent kinase 1 (CDK1) and peptidyl-prolyl cis-trans isomerase NIMA-interacting 1 (PIN1) as two previously uncharacterized regulators of pVHL stability in multiple cancer types harboring wild-type VHL including TNBC." (PMID 36813923, 2023). "The authors demonstrated higher VHL expression in acute myeloid leukaemia cells (AMLs) as compared with other cancer subtypes and normal tissues." (PMID 37667522, 2023).
cancer (continued). "Collectively, SEMA6A is identified as a novel target gene of VHL-HIF-2α with a cancer-promoting role in ccRCC." (PMID 36739418, 2023). "The TRAFTAC successfully degraded cancer-related NF-ĸB and brachyury TFs via VHL-dependent UPS in cervical cancer HeLa cells by NF-ĸB-TRAFTAC and Brachyury-TRAFTAC, respectively." (PMID 36986626, 2023). "Initial evidence suggests that miR-101-mediated downregulation of VHL induces HIF1α-driven cell cycle arrest and apoptosis in cancer cells under normoxia." (PMID 37583933, 2023). "In this study, we elucidated a distinct mechanism governing HIF-1α degradation in chronic hypoxic cancers, proposing its variability based on cancer metabolism and VHL activity." (PMID 37777750, 2023). "SK-RC-31 is a von Hippel-Lindau (VHL) mutant cancer cell line that excessively accumulates FGFR1 on PM as a result of defective endocytic internalization of surface FGFR1." (PMID 38136383, 2023). "Further preclinical studies including PDX in vivo animal models and clinical studies are warranted to explore the therapeutic benefits of targeting the PIN1/CDK1-pVHL axis in the treatment of multiple human cancers with wild-type VHL." (PMID 36813923, 2023). "Loss of the function of tumor suppressor protein VHL (pVHL) leads to accumulation and constitutive activation of hypoxia inducible factor 1α (HIF-1α) in cancer cells." (PMID 38273861, 2023). "For example, pattern 3 in VHL-wild samples is comprised of Cancer cell, Mast cell, NK cell, B cell, and T cell in the levels of types of cells, while in VHL-mutated samples, pattern 3 is constituted of Myeloid cell, NK cell, T cell, B cell." (PMID 36765369, 2023). "ccRCC is characterized by the loss of the VHL gene and further overexpression of hypoxia-inducible factor 1 alpha (HIF-1α), involved in cancer cell metabolic reprogramming." (PMID 37176098, 2023). "In this context, VHL has definitively been shown to be a strong potential candidate as a biomarker and/or a therapeutic target in cancer." (PMID 36036061, 2023). "Exosomes isolated from paired VHL(+) and VHL(−) cancer cell lines were assessed for physical, biochemical, and biological characteristics." (PMID 38139136, 2023). "In a novel metastasis model, VHL(−) cancer cells are the metastatic driver, while VHL(+) cells receive metastatic signals from VHL(−) cells and undergo aggressive transformation." (PMID 38139136, 2023). "The oligoTRAFTAC successfully degraded cancer-related cMYC and brachyury TFs by VHL-dependent UPS in HeLa and HEK293T cells, the degradation of which was abrogated by the E1 inhibitor MLN4924." (PMID 36986626, 2023). "This was presumably because VHL mutations were observed almost exclusively in RCC tumors, which carry a better prognosis than other cancers included in this cohort." (PMID 35798829, 2022). "In fact, in VHL-deficient tumors, HIF-1α protein level keeps at very high level, which is considered to be a major cause of cancer progression." (PMID 35732631, 2022). "Considering the HIF-1α-mediated upregulation of proangiogenic factors, an inhibitor of VHL would increase erythropoietin and can be used for the treatment of chronic anemia and cancer chemotherapy." (PMID 36235052, 2022). "VHL is characterized by the creation of various benign and malignant tumors, as well as cysts in multiple organs, and is passed down through generations in an autosomal dominant pattern with near-complete penetrance." (PMID 35901549, 2022). "VHL is characterized by the production of several benign and malignant tumors, as well as cysts in other organs." (PMID 35901549, 2022). "Of the 12 known PPGL susceptibility genes included in the multigene cancer panel used in the Hereditary Cancer Program, only SDHB and VHL were mutated." (PMID 36685941, 2022). "To gain further insight into the biological functions of MT1X, we used the human VHL defective ccRCC line 786O to detect some of the genes typically targeted by cancer therapies that are a part of the hypoxia pathway." (PMID 36149322, 2022).
cancer (continued). "Mechanistically, HIF drives lipid deposition and cancer progression in ccRCC via attenuation of fatty acid metabolism, and VHL restoration promotes fatty acid metabolism in 786-O cells." (PMID 35159281, 2022). "WSB1 promotes cancer progression by affecting the Von Hippel–Lindau tumor suppressor protein (pVHL) and upregulating hypoxia inducible factor-1α (HIF-1α) target gene expression." (PMID 35600960, 2022). "A VHL-recruiting ligand was conjugated to the 5′-endof the oligonucleotide to provide 47, which mediatedtarget degradation in two cancer cell lines via the UPS." (PMID 35816671, 2022). "Proof of concept has been demonstrated by targeted degradation of two cancer-relevant TFs, NF-κB and E2F, in a VHL E3 ligase and proteasome-dependent manner, thereby inhibiting cellular proliferation." (PMID 36499765, 2022). "Evidently, upregulation of miR-155 increases proliferation, invasion, migration, and tube formation in triple-negative BC (TNBC) and other cancers via targeting tumor suppressor von Hippel-Lindau (VHL)." (PMID 35992785, 2022). "For example, the unweighted studies found VHL and BRAF mutations incident at 7 and 2%, respectively, while our weighted study estimates these genes to be mutated in 1 and 8% of the cancer population." (PMID 34645806, 2021). "In fact, some genes, such as HRAS, YOD1, VHL, and CEBPA, were among the most important genes for several cancer types even though their number of mutations in TCGA is very small compared to other genes (ranging from the 4th to 16th percentile)." (PMID 34385450, 2021). "The fundamental function of VHL is targeting hypoxia inducible factors, HIFαs, for degradation, which accumulate in ccRCC, inducing genes essential for cancer progression, including angiogenesis, proliferation, and cancer metabolism." (PMID 33803184, 2021). "In contrast, a stem cell theory of cancer predicates that VHL is a passenger, an effect, and a marker of ccRCC." (PMID 34439162, 2021). "For example, VHL is frequently lost in certain cancer types, such as RCC; in such cases, a different E3 ligase such as CRBN would be more appropriate." (PMID 33627663, 2021). "In summary, our data demonstrated that MYC and HIF1α protein were degraded through proteasome dependent pathways, by the β-TrCP- and VHL-dependent mechanisms, respectively, in echinomycin-treated cancer cells." (PMID 33572152, 2021). "The VHL expression and p-VHL content determine the aggressive cancer behavior and are elevated in disseminated tumors." (PMID 34563045, 2021). "VHL E3 ligases complex is essential for regulating the expression of HIF1α that contributes to various cancers development." (PMID 35006464, 2021). "With the generation of HIF2α and glutaminolysis inhibitors, it is vital to understand the manner in which hypoxia pathways are regulated in a VHL mutant cancer such as ccRCC." (PMID 33799686, 2021). "The VHL expression and p-VHL content determined the aggressive cancer behavior and elevated in disseminated tumors." (PMID 34563045, 2021). "A decrease in the PDK kinase, PTEN, VHL mRNA level in primary cancers was noted, compared with metastases’ tissue." (PMID 34319022, 2021). "It should be noted that besides HIF1α, HIF2α and VHL also play a role in cancer development and progression." (PMID 34209205, 2021). "One of these VHL ligands, VH032, has been used to design the first VHL-based PROTAC, i.e., MZ1, which causes the degradation of bromodomain protein BRD4 in cancer cells." (PMID 34945781, 2021). "STF-31 is shown to act as a selective Glut1 inhibitor and inhibits the cell growth of the kidney and other types of cancer cells that lack the von Hippel–Lindau (VHL) tumor suppressor protein." (PMID 33053779, 2020). "Within VHL-positive cancer cell lines, HDAC4 inhibition by shRNA increases HIF-1α protein acetylation levels, while HDAC4 overexpression decreases HIF-1α acetylation levels." (PMID 33109235, 2020).